CNTNAP5 (contactin associated protein family member 5)
Description:
May play a role in the correct development and proper functioning of the peripheral and central nervous system and be involved in cell adhesion and intercellular communication.
Synonyms: CASPR5; FLJ31966
Tractability: Antibody: UniProt predicts a signal peptide or a membrane-spanning region.
Gene: Protein-coding gene on chromosome 2 (124,025,287 to 124,921,219, forward strand). Ensembl gene ENSG00000155052.
Subcellular location: Membrane
Subcellular location (Human Protein Atlas): Nucleoli fibrillar center; Nucleoplasm; Vesicles
Gene Ontology:
Biological process: nervous system development; signal transduction
Cellular component: fibrillar center; plasma membrane; synapse; membrane
Genetic constraint (gnomAD): Loss-of-function variants: 65 observed, 126.42 expected, observed/expected ratio (o/e) 0.51, 90% interval 0.42 to 0.63. The upper end of that interval is the gene's LOEUF score, 0.63, which puts it in group 2 of 6, group 1 being the genes least tolerant of losing a copy. Missense variants: 1,478 observed, 1,527.1 expected, observed/expected ratio (o/e) 0.97, 90% interval 0.93 to 1.01. Synonymous variants: 619 observed, 593.32 expected, observed/expected ratio (o/e) 1.04, 90% interval 0.98 to 1.12.
Gene-disease validity (ClinGen):
ClinGen rates the evidence that CNTNAP5 causes each of these diseases.
complex neurodevelopmental disorder (autosomal dominant): Disputed. A disorder that involves more than one phenotype associated with the central nervous system, including but not limited to intellectual disability, autism, and seizures (epilepsy).
Homologues: Orthologues: chimpanzee CNTNAP5 (99% identical), macaque CNTNAP5 (98% identical), dog CNTNAP5 (93% identical), pig CNTNAP5 (90% identical), rabbit CNTNAP5 (90% identical), guinea pig CNTNAP5 (87% identical), zebrafish cntnap5a (53% identical), zebrafish cntnap5b (53% identical), zebrafish cntnap5l (52% identical), Caenorhabditis elegans nlr-1 (23% identical). Paralogues in human: CNTNAP4 (58% identical), CNTNAP3 (53% identical), CNTNAP3B (52% identical), CNTNAP2 (50% identical), CNTNAP1 (38% identical), NRXN2 (25% identical), NRXN3 (24% identical), NRXN1 (24% identical), CNTNAP3C (21% identical), CUBN (16% identical), F8 (14% identical), HEPH (14% identical), and 23 more.
Diseases named in the same sentence as CNTNAP5 in open-access papers:
CNTNAP5 is named in the same sentence as 27 diseases in open-access papers, as found by Europe PMC text mining. Sharing a sentence is not in itself a finding about the gene and the disease. The quoted sentences say what the papers report.
autism (8 papers, 2010 to 2024). Persistent deficits in social interaction and communication and interaction as well as a markedly restricted repertoire of activity and interest as well as repetitive patterns of behavior. "Mutations in CNTNAP5 are associated with autism and neurodevelopmental disorders as well as glaucomatous neurodegeneration." (PMID 35932226, 2022). "CNTNAP5, encoding another neurexin-like protein, has also been linked with autism." (PMID 24387768, 2014). "In humans, genetic variation in Cntnap5 is associated with risk for Alzheimer's disease and bipolar disorder, while its deletion is associated with autism and dyslexia, suggesting the possibility that common pathways may come into play among different neurobiological disorders." (PMID 30568673, 2018). "Belonging to the neurexin family, the product of CNTNAP5 functioned as cell adhesion molecules in the nervous system and participated in diseases such as autism, Alzheimer’s disease, and schizophrenia." (PMID 32789468, 2020). "However, the two brothers with autism also inherited a deletion that disrupts CNTNAP5 from their father, who had dyslexia as a child." (PMID 38526744, 2024). "We also assessed the genomic background in the autism family with the IMMP2L-DOCK4 deletion and detected a second rare microdeletion disrupting CNTNAP5 in the ASP." (PMID 20346443, 2010). "Notably, 22 out of the 45 reported (candidate) genes are known to be related to a broader phenotype than DLD, including intellectual disability, epilepsy, and/or autism (e.g., GRIN2A, CNTNAP2, CNTNAP5, AUTS2)." (PMID 38298611, 2024).
bipolar disorder (4 papers, 2014 to 2024). A disorder of the brain that causes unusual shifts in mood, energy, activity levels and the ability to carry out day-to-day tasks. "The cross-referencing with the PheWAS catalogue revealed that CNTNAP5 polymorphisms are not only associated with glaucoma but also with several other neurodevelopmental and neurological disorders, such as schizophrenia, bipolar disorder, epilepsy, and Alzheimer’s disease." (PMID 39637236, 2024). "Comparison with other published GWA studies for bipolar disorder, excluding those with partial overlap of subjects, appears to corroborate several loci and candidate genes, including CNTNAP5, ZNF804A, ZNF659, SORCS2, and ZNF536." (PMID 24387768, 2014).
schizophrenia (4 papers, 2010 to 2024). A major psychotic disorder characterized by abnormalities in the perception or expression of reality. "Additionally, mining of the phenotype-wide association study (PheWAS) catalog revealed significant genetic associations between variants in the CNTNAP5 locus and several neurological disorders including epilepsy, schizophrenia and Parkinson’s disease." (PMID 39637236, 2024). "Common variants implicating CNTNAP5 have previously been associated with the posterior cortical atrophy variant of AD, BIP, and response to antipsychotic treatment in schizophrenia, while rare variants within CNTNAP5 have previously been associated with autism spectrum disorders." (PMID 30930738, 2019). "A nonsynonymous SNP in CNTNAP5 was recently identified in a genome-wide pharmacogenomic study as potentially influencing the effect of the drug risperidone on negative symptoms in schizophrenia." (PMID 20346443, 2010).
glaucoma (2 papers, 2024). Increased pressure in the eyeball due to obstruction of the outflow of aqueous humor. "Altogether, this study, for the first time, provides direct evidence of CNTNAP5 involvement in neuronal loss in the retina and glaucoma." (PMID 39637236, 2024). "Our study highlights CNTNAP5 as a novel gene associated with primary angle-closure glaucoma (PACG) with a potential role in retinal neurodegeneration." (PMID 39637236, 2024). "CNTNAP5 is known for its roles in cell adhesion and cellular communication within the nervous system and some studies have found its correlation with glaucoma." (PMID 39554798, 2024). "Together, these findings suggest that CNTNAP5 may contribute to the pathogenesis of glaucoma through its impact on retinal integrity and apoptosis." (PMID 39637236, 2024). "Future studies involving 3C analysis and mammalian models could validate these findings and provide deeper insights into the regulatory mechanisms of CNTNAP5 in glaucoma." (PMID 39637236, 2024).
Intellectual disability (2 papers, 2023 to 2024). "Familial deletions, GWAS, and Multivariate and Collapsing (CMC) burden tests, in CNTNAP5 have mainly found associations with atypical neurodevelopment and intellectual disability." (PMID 36607984, 2023).
posterior cortical atrophy (2 papers, 2019 to 2020). Posterior Cortical Atrophy (PCA) is a rare progressive neurodegenerative disorder with a typical onset between 50-65 years of age characterized by progressive impairment of higher visual processing skills and other posterior cortical functions without any evidence of ocular abnormalities. "However; the CNTNAP5 gene has previously been associated with the posterior cortical atrophy variant of AD at genome-wide significance and with BIP." (PMID 30930738, 2019). "Variants in the FAM110A (rs1014897), the CNTNAP5 (rs76854344) and NTM (rs1040103) genes associated with this inflammatory module have been previously linked to posterior cortical atrophy, LOAD, and white blood cell count." (PMID 32492070, 2020).
adenoma (1 paper, 2020). A neoplasm arising from the epithelium. "Lesion-specific mutations in JMJD6, CNTNAP5 (adenoma-enriched), and GSG1L (carcinoma-enriched) were also identified." (PMID 32023847, 2020).
oesophageal adenocarcinoma (1 paper, 2015). "CNTNAP5 was highlighted as relatively frequently mutated in exome sequencing of oesophageal adenocarcinoma." (PMID 26159513, 2015).
retinal disease (1 paper, 2024). "Most notably, HumanBase analysis also predicted an association between CNTNAP5 and retinal disease, with a confidence score of 0.11." (PMID 39637236, 2024).
upper tract urothelial carcinoma (1 paper, 2020). "The expression level of CNTNAP5 in the kidney is relatively low but still detectable, and only one study reported a SH3KBP1–CNTNAP5 fusion in upper tract urothelial carcinoma." (PMID 32789468, 2020).
cancer (3 papers, 2016 to 2022). A tumor composed of atypical neoplastic, often pleomorphic cells that invade other tissues. "Other frequently mutated EAC driver genes included NOTCH1 (N=8 cancers), ARID1A (N=7), CNTNAP5 (N=3), PIK3CA (N=3) and SMARCA4 (N=3)." (PMID 27045317, 2016).
neurodevelopmental disorder (2 papers, 2022 to 2023). A behavioral and cognitive disorder with onset during the developmental period that involves impaired or aberrant development of intellectual, motor, or social functions. "It would also be of great interest to conduct similar studies for other members of the Contactin Associated Protein family, which have also been associated with neurodevelopmental disorders such as ASD, especially Caspr3/CNTNAP3, Caspr4/CNTNAP4, and Caspr5/CNTNAP5." (PMID 36793543, 2023).
neurological disorders (1 paper, 2024). "Earlier reports detected possible connection between rare variants in CNTNAP5 with neurodevelopmental disorders or neurological diseases." (PMID 39637236, 2024).
tumor (1 paper, 2025).
CNTNAP5 also shares sentences with these, for which no sentence is quoted: dyslexia (4 papers); Alzheimer disease (3); autism spectrum disorder (2); epilepsy (2); type 2 diabetes (2); Anxiety (1); cervical cancer (1); congenital glaucoma (1); insomnia (1); Obesity (1); Parkinson disease (1); primary angle-closure glaucoma (1); retinal degeneration (1).